ENSG00000252291
Gene: Small nucleolar RNA gene on chromosome X (6,061,644 to 6,061,749, reverse strand). Ensembl gene ENSG00000252291.
Homologues: Orthologues: rat LOC120102627 (70% identical). Paralogues in human: SNORA31B (80% identical), SNORA31 (66% identical).